PLK1 (polo like kinase 1)
Diseases named in the same sentence as PLK1 in open-access papers (continued):
Sharing a sentence is not in itself a finding about the gene and the disease.
breast carcinoma (continued). "Furthermore, PLK1 mRNA expression was lower in the normal breast epithelial cells (MCF10A) compared to that in the different breast cancer cell lines (BT-20, MCF-7, SK-BR-3 and MDA-MB-231)." (PMID 38186570, 2023). "PLK1 silencing attenuates cell proliferation and growth and induces apoptosis in breast cancer." (PMID 36993976, 2023). "Correlation of PLK1 protein expression with clinico-pathological parameters in breast cancer." (PMID 38234395, 2023). "The overexpression of PLK1 is linked to the formation, metastasis, prognosis and overall survival rate of various tumor types, including breast cancer, non-small cell lung cancer, prostate cancer, and non-Hodgkin lymphoma." (PMID 38037110, 2023). "In addition, the Conceptions of Learning and Teaching (COLT) analysis of essential genes in 29 breast cancer lines identified PLK1 as a hit in 27 (93%) of these lines, including MDA-MB-468 and MDA-MB-231 TNBC cells." (PMID 35454120, 2022). "At present, researchers elucidate the roles of PLK1 in the development of breast cancer." (PMID 35456460, 2022). "This prompted us to investigate how PLK1 inhibition with the target-specific inhibitor NMS-P937 would impact breast cancer cells, and how miRNAs may influence the overall response of these cells to this inhibition." (PMID 34561554, 2022). "This suggests the preclinical validity of PLK1 as a potential molecular target for breast cancer." (PMID 35454120, 2022). "PLK1 inhibition also sensitizes breast cancer cells to radiation by suppressing autophagy." (PMID 36393842, 2022). "In addition, researchers have reported the transcriptional action of PLK1 on the regulation of ER mediated by human breast cancer cells, and proposed the mechanism of PLK1 as a mediator of interphase transcription regulators in animal mammalian tumors." (PMID 35456460, 2022). "CCNE1 and PLK1 were identified as potential antigens in breast cancer." (PMID 36393842, 2022). "It has been reported that PLK1 is frequently over-expressed in numerous cancers (such as esophageal cancer, colon cancer, breast cancer, non-small cell lung cancer, endometrial cancer, etc.), and facilitates the occurrence and progress of these cancers acting as an oncogene." (PMID 36618405, 2022). "In addition, the Kaplan–Meier survival analysis of fifteen hub genes demonstrated that the high expression of CCNB1 and PLK1 was significantly correlated with the low survival rate of breast cancer patients." (PMID 35456460, 2022). "Furthermore, the expression of PLK1 was higher in basal breast cancer cell lines than in luminal cell lines." (PMID 36008466, 2022). "In addition, the upregulation of genes upon PLK1 inhibition correlates with their expression in normal breast tissue and with better overall survival in breast cancer patients." (PMID 36008466, 2022). "BI 2536, a Plk1 enzyme inhibitor, was suggested to induce mitotic arrest and a subsequent surge in apoptosis and suppress the expression of epithelial-mesenchymal transition markers and 3D spheroid formation in breast cancer." (PMID 36016611, 2022). "Indeed, PLK1 inhibition also led to upregulation of PD-L1 expression in melanoma and breast cancer cells with varying PD-L1 baseline expression." (PMID 35871223, 2022). "In conclusion, CCNE1 and PLK1 were identified as potential antigens in breast cancer." (PMID 36393842, 2022). "Previously, a genome-scale shRNA (short hairpin RNA) screen using the SUM series of human basal breast cancer cell lines was conducted and polo-like kinase 1 (PLK1), which is essential for survival, was identified, thus underscoring its relevance in breast cancer growth." (PMID 35454120, 2022).
breast carcinoma (continued). "The inhibition of PLK1 can repress the mitophagy of breast cancer cells." (PMID 34115550, 2021). "Importantly, CHEK1 and PLK1 were found to be poor prognostic biomarkers for the survival of breast cancer patients, further supporting that enhanced DNA damage repair mechanisms in cancer cells play a catastaltic role in efficient radiotherapy." (PMID 33898418, 2021). "Finally, a clonogenic assay was used to further evaluate the synergy effects between the L1 and Plk1 inhibitors to inhibit colony formation of breast cancer CAL51 cells after a 12 h drug exposure." (PMID 34493069, 2021). "Some reports demonstrated that suppression of PLK1 inhibited the mitophagy of breast cancer cells." (PMID 34115550, 2021). "While, Polo-like kinase 1 (PLK1) can induce the mitophagy of breast cancer cells." (PMID 34115550, 2021). "Recent evidence showed that miRNA-100 downregulates Polo-like kinase 1 in basal-like cancer, blocking the maintenance and expansion of breast cancer stem cells (BrCSCs), inducing BrCSC differentiation, thus favoring the transition from undifferentiated tumors into well-differentiated ones." (PMID 34442460, 2021). "In addition to the mentioned studies, an AS1411 aptamer-functionalized nanoliposome-based delivery system has been developed for the co-delivery of PTX and polo-like kinase 1-targeted siRNA (PLK1-targeted siRNA) to breast cancer cells." (PMID 34723284, 2021). "As L1 displayed specific toxicity in a breast cancer cell line, we further compared the synergistic effects of L1 and the Plk1 inhibitor between a cancer cell line and a non-cancer cell line, with various doses of L1 in the absence (black) or presence (red) of 0.1 nM BI2536." (PMID 34493069, 2021). "Plk1 was proven as amongst the utmost striking receptor for breast cancer treatment." (PMID 33247393, 2020). "Using Kaplan-Meier mapping instrument to access the gene chip database, we found that CDK1, PLK1, and CDC20 are associated with poor prognosis of breast cancer, which suggests that these three genes may be valuable genes." (PMID 32848800, 2020). "Importantly, PLK1 has been shown to play a role in mediating tamoxifen resistance in ER+ breast cancer cells, and thus we will conduct additional studies evaluating the role of PLK1 as a novel target for the ER+ breast cancer resistant to CDK4/6 inhibition." (PMID 32344635, 2020). "Finally, the Western blot analysis confirmed the effect of podophyllotoxin on breast cancer by interfering with PLK1 on the protein level." (PMID 32848800, 2020). "Thus, we not only elucidated the relative sensitivity of a panel of breast cancer cell lines to Plk1 targeted drugs, but also attempted to determine if Plk1 inactivation sensitizes breast cancer cells to taxanes." (PMID 31751384, 2019). "In addition, Plk1 regulates cell surface levels of β1‐integrin and invasion by phosphorylating vimentin in breast cancer cells." (PMID 31040125, 2019). "In the present study, we found that AME can cause S-phase arrest of breast cancer cells, downregulate the expression of CDC20, AURKB, PLK1, CCNB2, and TOP2A, and upregulate the expression of GADD45A, eventually inhibiting the proliferation of breast cancer cells." (PMID 31275405, 2019). "And in HER-2-positive breast cancer, PLK1-siRNA suppresses cancer growth and metastasis." (PMID 31871499, 2019). "Evidence also revealed that breast cancer cells with treatment of siRNAs targeting PLK1 could improve the sensitivity toward paclitaxel and Herceptin." (PMID 29467930, 2018). "Finally, to investigate the clinical significance of PLK1 expression in breast cancer, we grouped tumors into those with low PLK1 expression (bottom quartile PLK1 expression) and those with higher PLK1 expression (remaining quartiles)." (PMID 30069007, 2018).
breast carcinoma (continued). "Moreover, the percentage of cells proliferating in these tumors was significantly lower than in Kras or Her2 tumors alone, suggesting that in mammary tumors Plk1 overexpression results in increased CIN and growth inhibition." (PMID 30069007, 2018). "However, the clinicopathological and prognostic implications of PLK1 in breast cancer (BC) have yet to be unveiled." (PMID 28915707, 2017). "Moreover, the AsiC-induced knockdown of the mitosis regulator PlK1, suppressed tumor-initiating cells (TICs) of epithelial breast cancer cells as shown in in vitro functional assays (colony and mammosphere formation)." (PMID 28792479, 2017). "Consistent with this notion, a recent study reported that PLK1 depletion, mediated by PLK1 siRNA delivered by an antioxidant nanoparticle platform, inhibits lung metastasis and prolongs overall survival in a mouse model of breast cancer metastasis." (PMID 28953239, 2017). "PLK1 is overexpressed in a variety of malignancy including breast cancer." (PMID 29383106, 2017). "To analyze FBXW7 expression and its relation to the relative abundance of substrates, and with prognostic variables in breast cancer, we performed immunohistochemistry for FBXW7, AURKA, Cyclin E, MCL1 and PLK1 in tissue microarrays containing up to 296 samples of breast carcinomas." (PMID 27409838, 2016). "Breast cancer patients expressing elevated PLK1 expression show significantly reduced survival." (PMID 26863570, 2016). "We conclude that FBXW7 regulates the response to paclitaxel by targeting MCL1 and PLK1 in breast cancer cells and thus targeting these substrates may be a valuable adjunct for paclitaxel treatment." (PMID 27409838, 2016). "Furthermore, we demonstrated that PLK1 is also involved in paclitaxel resistance because decreasing the levels of PLK1 by siRNA sensitized resistant breast cancer cells to treatment with paclitaxel." (PMID 27409838, 2016). "Reintroducing FBXW7 activity or interfering MCL1 and PLK1 restores paclitaxel sensitivity in resistant cells and thus, targeting these substrates may be a valuable adjunct to paclitaxel for the treatment of breast cancer." (PMID 27409838, 2016). "PTC-209 strongly inhibits growth of colon cancer cells and CSC phenotype, and BMI1 downregulation using siRNA approach or its inhibition by histone deacetylase inhibitors (HDACi) and PLK1 inhibitors is known to induce premature senescence in normal and breast cancer cells." (PMID 27105531, 2016). "It is thus possible that, like mTOR, PLK1 may also mediate the effect of miR-100 on breast cancer sensitivity to paclitaxel, though this remains to be determined." (PMID 26744318, 2016). "Finally, this transition fuels malignant properties of breast cancer cells and render them resistant to ATP competitive Polo-like kinase 1 inhibitors BI 2535 and BI 6727." (PMID 26439686, 2015). "PLK1 is often overexpressed in several tumors including breast cancer." (PMID 25286005, 2014). "Interestingly, the analysis of gene expression databases of different cohorts of breast cancer patients reveals that those expressing high levels of PLK1, BUB1 or CCNA2 exhibit lower disease-free survival when compared to those expressing low levels." (PMID 23125021, 2012). "David functional annotation analysis showed 75% genes of the PLK1-MCM complex-SKP2 subnet in breast cancer patient datasets and 70.7% genes of the PLK1-MCM complex-SKP2 subnet in NSCLC patient datasets are involved in the Reactome pathway of “Cell Cycle, Mitotic”." (PMID 22838965, 2012). "In this study, the expression of PLK1 in different breast cancer subtypes was confirmed, and its inhibition led to growth inhibition and apoptosis on all breast cancer cell lines tested, indicating a broad application in breast cancer treatment." (PMID 22309939, 2012).
breast carcinoma (continued). "Specifically, our discovery of suspension-induced up-regulation of TrkB and NTF3 in breast cancer cells via NF-κB supports earlier work showing that polo-like kinase 1 (PLK1) is transcriptionally activated by RelA in suspended esophageal squamous cell carcinomas, leading to anoikis resistance." (PMID 23185507, 2012). "Further studies were focused on polo-like kinase 1 (PLK1), including its expression in breast cancer cell lines, effect on the CD44high/CD24-/low TIC subpopulation, growth inhibition, mammosphere formation, and apoptosis, as well as the activity of the PLK1 inhibitor, BI 2536." (PMID 22309939, 2012). "Hence, aberrations of PLK1 and PLK4 can cause centrosome-related errors, which in turn impact genomic stability and cell division accuracy and thereby play a vital role in cancer, including breast cancer." (PMID 38606093, 2024). "Moreover, the identification of inhibitors that targeting CCNB1 and PLK1 might provide a new idea for treating breast cancer." (PMID 35456460, 2022). "This trend suggests that PLK1 could be a potential direct or indirect therapeutic target in HR-positive breast cancer even though the gene expression analyses of the current study were derived from breast cancer cohorts that were not exposed to CDK4/6 inhibitors." (PMID 35008374, 2022). "Moreover, CCNB1 and PLK1 are highly expressed in all breast cancer stages, suggesting that they could be further studied as potential drug targets." (PMID 35456460, 2022). "Furthermore, recent findings suggest that in breast cancer, the miR-100 may act as a pro-differentiating agent for cancer stem cell modulating Wnt/β-catenin pathway and Polo-like kinase 1 gene." (PMID 34442460, 2021). "Interestingly, PLK1 has been proposed to be the functional partner of PKMYT1 in regulating cell cycle, and PLK1 is also closely related to breast cancer, implying that PLK1 and PKMYT1 may play an cooperative role in the development of breast cancer." (PMID 31837068, 2020). "Polo-like kinase 1 (PLK1) is a serine/threonine kinase that is implicated in tumorigenesis and serves as a prognostic marker for worsened patient outcomes in multiple cancers, including non-small cell lung cancer (NSCLC), head and neck squamous cell carcinomas, and breast cancer." (PMID 32805721, 2020). "CDC20, CDK1, and PLK1 may be the targets of podophyllotoxin in breast cancer." (PMID 32848800, 2020). "Recently, PLK1 has been found to be overexpressed in many types of human cancers such as hepatocellular carcinoma, glioma, colorectal cancer, gastric cancer, pancreatic cancer, lymphomas, ovarian cancer, bladder cancer, prostate cancer, breast cancer, and esophageal cancer." (PMID 28724602, 2017). "For example, PLK1 is overexpressed in a variety of cancers, including prostate cancer, non-small cell lung cancer, head and neck cancer, esophageal and gastric cancer, melanoma, breast cancer, ovarian cancer, endometrial cancer, colorectal cancer, glioma, thyroid cancer, and hepatocellular cancer." (PMID 28953239, 2017). "Thus, we may conclude that MCL1 and PLK1 are contributors to the development of paclitaxel resistance in breast cancer cells." (PMID 27409838, 2016). "It was known that the two kinases AURKA and PLK1 were upregulated in a number of tumors including colorectal and breast cancer, as a result of perturbations in centrosome function and spindle assembly that could promote tumorigenesis by enhancing genome instability." (PMID 24876664, 2014). "Thus, PLK1 could be a potential therapeutic target for the treatment of TNBC as well as other subtypes of breast cancer." (PMID 22309939, 2012).
breast carcinoma (continued). "PLK1 inhibition could be a common target for gastric adenocarcinoma, bladder cancer, colon cancer, hepatocellular carcinoma, medullary thyroid carcinoma, esophageal cancer, pancreatic cancer and in some types of non-Hodgkin lymphomas and breast cancer." (PMID 20805891, 2010). "The study focuses on exploring the therapeutic potential of Caryota urens fruit against breast cancer, specifically targeting cell cycle genes CDK1, CDC25A, and PLK1 through bioinformatics, network pharmacology, and in vitro validation." (PMID 40081286, 2025). "This study enhances breast cancer research by revealing Episesamin's ability to specifically target and downregulate key cell cycle genes CDK1, CDC25A, and PLK1." (PMID 40081286, 2025). "Meanwhile, in addition to PLK1, the mechanism of action of other genes in the core gene cluster regulated by DHIE and their interactions with each other in breast cancer still deserve to be investigated." (PMID 40093330, 2025). "A recent analysis of breast cancer samples integrated in The Cancer Genome Atlas (TCGA) revealed that KIF2C, along with two cell cycle master regulators CCNB1 (cyclin B1) and Plk1, is a promising target for breast cancer therapy." (PMID 38344808, 2024). "SAMD5 regulation of PLK1 was validated, and the dynamic effects of SAMD5/PLK1 on breast cancer cell phenotypes, c-Myc signaling, and in vivo tumor growth in a mouse model were explored." (PMID 39524172, 2024). "The expression levels of PLK1 and IFNG in breast cancer tissues were significantly higher than those in the paired adjacent normal tissues." (PMID 39314848, 2024). "We demonstrate three approaches (PAI1-targeted, PLK1-targeted, and epigenetics-targeted) to restore HER2 therapy sensitivity in a panel of fibroblast-protected HER2+ breast cancer cells." (PMID 39513002, 2024). "PLK1 exhibits overexpression in breast cancer, particularly in TNBC; therefore, PLK1 was selected for further investigations." (PMID 39524172, 2024). "PLK1, a potential target for cancer therapy, was revealed for the first time to regulated by LAS in breast cancer." (PMID 38495493, 2024). "Therefore, PLK1 may mediate the functions of SAMD5 in breast cancer cells." (PMID 39524172, 2024). "Our data-driven framework of proteomic profiling in breast cancer cells identified the proteolytic degradation regulator PAI1 and the cell cycle regulator PLK1 as predictors of fibroblast-mediated treatment resistance." (PMID 39513002, 2024). "PLK1, IFNG, S100B, and IRS2 were expressed at significantly different levels between breast cancer and normal breast tissues." (PMID 39314848, 2024). "This study aimed to evaluate the efficacy of combining alpelisib with a highly specific PLK1 inhibitor, onvansertib, in PIK3CA-mutant HR+ breast cancer preclinical models." (PMID 39409880, 2024). "Polo-like kinase 1 (PLK1) plays a crucial role in cell cycle regulation and its overexpression correlates with poor prognosis in breast cancer patients." (PMID 38474678, 2024). "Previous studies reported that PLK1 promotes cell growth and epithelial–mesenchymal transition through the CRAF-MEK-ERK pathway in various cancers, including gastric cancer, breast cancer, and prostate cancer." (PMID 39451218, 2024). "Collectively, these data indicate that combined inhibition of PLK1 and PI3K synergistically inhibits cell proliferation and impairs the clonogenicity of ER+ breast cancer cell lines harboring PI3K-pathway alterations." (PMID 39409880, 2024). "PLK1, AURKB, and survivin are overexpressed in triple-negative breast cancer (TNBC), an aggressive breast cancer subtype." (PMID 36627281, 2023). "When kaempferol was administered to the human breast cancer cell line MCF-7, it suppressed the expression of PLK-1, a protein-like kinase that has been shown to control mitotic development and to be elevated in several human cancers." (PMID 37226153, 2023).